UGDH (UDP-glucose 6-dehydrogenase)
Diseases named in the same sentence as UGDH in open-access papers (continued):
Sharing a sentence is not in itself a finding about the gene and the disease.
ovarian carcinoma (continued). "We predict that knockdown of UGDH decreased the levels of GAGs in ovarian cancer and therefore affected the ovarian cancer metastatic ability." (PMID 32893977, 2020). "Our data demonstrate that knockdown of UGDH attenuated the migratory ability of ovarian cancer cells." (PMID 32893977, 2020). "In this study, immunohistochemistry (IHC) was conducted to evaluate the expression level of UGDH in ovarian cancer tissue." (PMID 32893977, 2020). "Collectively, our results demonstrated that knockdown of UGDH not only attenuated ovarian cancer migration and invasion abilities in vitro but also decreased ovarian tumour growth in a xenograft model in vivo." (PMID 32893977, 2020). "Interestingly, in ovarian cancer, UGDH KD has been shown to negatively regulate levels of activated (phosphorylated) ERK with direct impacts on expression of MMP-2, MMP-9 and EMT-related factors further downstream." (PMID 37769033, 2023). "In conclusion, we demonstrated that UGDH is related to high invasiveness in ovarian cancer and provided evidence supporting that UGDH participates in cancer migration, invasion and cell proliferation in ovarian cancer." (PMID 32893977, 2020). "We hypothesized that knockdown of UGDH by short interfering RNA (siRNA) could similarly reduce cell proliferation in ovarian cancer." (PMID 32893977, 2020). "UGDH was knocked by siRNA in three ovarian cancer cell models, TOV21G, A2780 and HeyA8 cells." (PMID 32893977, 2020). "The expression level of UGDH in TOV21GHI cells was significantly higher than that in TOV21GLI cells, suggesting that UGDH is overexpressed in a highly aggressive ovarian cancer cell line." (PMID 32893977, 2020). "By performing immunohistochemical staining with tissue microarray, we found overexpression of UGDH in ovarian cancer tissue, but not in normal adjacent tissue." (PMID 32893977, 2020). "Our data demonstrated that UGDH overexpressing TOV21GHI cells express higher levels of phosphorylated‐ERK, MMP‐2, SIP‐1 and SNAIL, whereas knockdown of UGDH leads to decreases in these markers, indicating that UGDH is involved in regulating ERK, MMP‐2 and EMT markers in ovarian cancer." (PMID 32893977, 2020). "While not as clear mechanistically, UGDH KD has also been shown to decrease expression of EMT transcription factors SNAIL, SIP-1, and matrix mellatoprotease protein 2 (MMP2) in ovarian cancer cell models." (PMID 37769033, 2023).
developmental delay (5 papers, 2020 to 2025). "Here, we report an allelic series of germline recessive mutations in UGDH in 36 cases from 25 families presenting with epileptic encephalopathy with developmental delay and hypotonia." (PMID 32001716, 2020). "Finally, a condition with severe developmental delay and epileptic seizures has been described in individuals with pathogenic variants in UGDH, a gene coding for UDP-glucose dehydrogenase that forms UDP-GlcA from UDP-glucose." (PMID 34828260, 2021).
prostate carcinoma (5 papers, 2014 to 2025). A carcinoma that arises from epithelial cells of the prostate gland. "UGDH is elevated in multiple cancers, including prostate cancer, and is functionally implicated in castration resistant recurrence." (PMID 41110727, 2025). "In contrast, UGDH is elevated in CR prostate cancer and the increase in those cells is associated with higher hyaluronan production and proteoglycan expression." (PMID 34548906, 2021). "All pairs showed changes in UGDH and associated enzymes and metabolites that were consistent with those we found in an isogenic androgen dependent (AD) and CR LNCaP prostate cancer model." (PMID 34548906, 2021). "We previously reported a detailed examination of gene expression and metabolite levels in pathways impinging on the enzyme UGDH in the LNCaP model of androgen dependent (AD, also termed castration sensitive) and castration resistant (CR) prostate cancer." (PMID 34548906, 2021). "Our previous studies in prostate cancer models found that UGDH levels are androgen stimulated and increased UGDH can drive intracellular steroid depletion through elimination as androgen-glucuronides." (PMID 34548906, 2021). "Specifically for prostate cancer, the leading hypothesis is that differential expression of UGDH can modulate how UDP-sugars flux through hormonal processing and ECM production pathways." (PMID 37769033, 2023). "Indeed, the authors demonstrated that over-expressing UGDH in both androgen responsive and castrate resistant prostate cancer cell lines can induce androgen independent growth." (PMID 37769033, 2023). "UGDH regulation of glucuronidation therefore could be a mechanism to promote androgen response deregulation and increase castration resistance within hormonally responsive prostate cancer." (PMID 37769033, 2023). "Similar results were observed in prostate cancer, where downregulation of UGDH promotes androgen-independent tumor cell growth by increasing available levels of intracellular androgen, which is why it could be considered as a detection marker for this type of cancer." (PMID 33572239, 2021). "Moreover, evidence also indicates that UGDH determines hyaluronan synthesis in prostate cancer cells, which thus promotes the metastasis progression of the cancer cells, while the stimulated UGDH expression by TGF-β promotes hyaluronan production in articular surface cells in chicks." (PMID 25465897, 2014). "UDP-glucose dehydrogenase (UGDH) produces UDP-glucuronate, the essential precursor for glucuronidation, and its expression is elevated in prostate cancer." (PMID 34548906, 2021). "For prostate cancer, higher levels of UGDH have been observed in cancerous prostate acini than non-cancerous prostate tissue—a finding that established UGDH as a potential biomarker for PC." (PMID 37769033, 2023).
lung adenocarcinoma (4 papers, 2022 to 2023). A carcinoma that arises from the lung and is characterized by the presence of malignant glandular epithelial cells. "This connection mechanistically explained the increased in vitro and in vivo tumor cell migration and metastasis associated with higher levels of UGDH in lung adenocarcinoma." (PMID 37769033, 2023). "In lung adenocarcinoma positive nuclear UGDH localization correlated with lymphatic and vascular invasion, larger tumor size, higher stage, and poor differentiation." (PMID 37858159, 2023). "In patients with lung adenocarcinoma, the presence of UGDH in the nucleus is correlated with poorly differentiated cells and larger tumors and could indicate overall reduced survival." (PMID 35240026, 2022). "We also examined the subcellular localization of UGDH in the TMAs to determine if it had a prognostic indication for EOC, similar to what was reported for lung adenocarcinoma." (PMID 37858159, 2023). "While UGDH phosphorylation has not been mechanistically explored in other cancers or reported in normal physiology, this study did correlate phosphorylated UGDH to a metastatic and pro-EMT phenotype of lung adenocarcinoma." (PMID 37769033, 2023).
colorectal cancer (3 papers, 2021 to 2023). A primary or metastatic malignant neoplasm that affects the colon or rectum. "The relationship of UGDH and HA metabolism has also been shown to play a role in tumor aggressiveness in melanoma, colorectal cancer, nasopharyngeal and primary brain tumors." (PMID 37769033, 2023). "Similar phenotypic findings have been reported in colorectal cancer with UGDH KD effectively decreasing cell migration and motility in both transwell migration assays and 3-D collagen gels." (PMID 37769033, 2023). "The effect of UGDH in promoting metastasis in colorectal carcinoma through GAG production has been previously reported." (PMID 36233276, 2022).
Epileptic encephalopathy (3 papers, 2020 to 2025). A condition in which epileptiform abnormalities are believed to contribute to the progressive disturbance in cerebral function. "Based on the incidence of variants observed, UGDH mutations are likely to be a frequent cause of recessive epileptic encephalopathy." (PMID 32001716, 2020). "UGDH-related disorders form a specific subtype of congenital disorders of glycosylation that exhibit a spectrum of symptoms and variable response to standard treatments for epileptic encephalopathy and/or cardiac valve defects." (PMID 40879729, 2025). "This suggests that the severity of the epileptic encephalopathy may correlate with the amount of residual UGDH activity, the extent of which may be sufficient to allow gastrulation to take place during early human embryonic stages but may be limiting for neuronal development thereafter." (PMID 32001716, 2020).
hepatoma (3 papers, 2022 to 2025). "UDP‐glucose 6‐dehydrogenase (UGDH)‐mediated UDP‐glucuronic acid (UDP‐GlcUA) accumulation promoted hepatoma cell migration upon GSTZ1 loss." (PMID 35979621, 2022). "Inhibition of either UGDH or TGFβR1 is known to impair the metastasis of hepatocellular carcinoma metastasis." (PMID 40166083, 2025).
osteoarthritis (3 papers, 2014 to 2025). A noninflammatory degenerative joint disease occurring chiefly in older persons, characterized by degeneration of the articular cartilage, hypertrophy of bone at the margins and changes in the synovial membrane. "The objective of this study was to investigate the possible role of UDP-glucose dehydrogenase (UGDH) in osteoarthritis (OA) and uncover whether, furthermore how interleukin-1beta (IL-1β) affects UGDH gene expression." (PMID 25465897, 2014). "For the “Erasers”, compounds such as the p300 inhibitor A485 can inhibit UDP-glucose dehydrogenase (UGDH) lactylation in vitro and in vivo, rescuing chondrocyte extracellular matrix degradation and delaying the progression of osteoarthritis (OA)." (PMID 40511385, 2025).
clear cell carcinoma (2 papers, 2020 to 2024). "IHC results indicated that UGDH was highly expressed in over 60% of clear cell carcinoma and mucinous adenocarcinoma tissue samples compared to in adjacent normal tissue." (PMID 32893977, 2020). "All adjacent normal tissues (n = 10) showed weak expression of UGDH, whereas increased expression was observed in malignant tumours, including clear cell carcinoma and mucinous adenocarcinoma tissues." (PMID 32893977, 2020). "Tissue microarray analysis showed that UGDH is highly expressed in clear cell carcinoma and mucinous carcinoma tissue samples, but not in normal adjacent tissue." (PMID 32893977, 2020).
dwarfism (2 papers, 2020 to 2022). "A structural variant affecting UGDH has been associated with disproportional dwarfism in cats." (PMID 36531249, 2022). "In addition, as a novel gene association with dwarfism, UGDH should also be screened for variants in undiagnosed human dwarf patients." (PMID 33090996, 2020). "Two potential outcomes from the analysis are 1) the SV itself causes a gain of function for UGDH with activity specific to growth of long bones, or 2) feline UGDH plays a unique feline specific role in bone growth, where loss of function of this gene causes feline dwarfism." (PMID 33090996, 2020). "Moreover, structural variant analysis revealed a novel variant for feline dwarfism in UGDH, a gene that has not been associated with dwarfism in any other species, suggesting a role for UGDH in cases of undiagnosed dwarfism in humans." (PMID 33090996, 2020). "Importantly, UGDH has not yet been associated with human dwarfism and should be screened in undiagnosed patients." (PMID 33090996, 2020).
atherosclerosis (1 paper, 2022). A disease characterized by the build-up of fatty material and calcium deposition in the arterial wall resulting in partial or complete occlusion of the arterial lumen. "UGDH is an enzyme involved in the synthesis of glycosaminoglycans (GAGs) and an overall decrease in GAGs occurs as atherosclerosis progresses." (PMID 35673616, 2022).
breast adenocarcinoma (1 paper, 2021). "In the present work, we studied the modulation of UGDH using the breast adenocarcinoma cell line MDA-MB-231 as tumor model, with characteristics of lack of response to hormonal therapy and increased aggressiveness." (PMID 33572239, 2021).
chondrodysplasia (1 paper, 2021). "A form of chondrodysplasia that represents the breed standard in short-legged Munchkin cats is caused by a large deletion within the UGDH gene encoding UDP-glucose 6-dehydrogenase (OMIA 000187-9685)." (PMID 34946872, 2021).
dystroglycanopathy (1 paper, 2025). "However, a number of UGDH variants have been reported and characterized as causative agents of congenital defects in cardiac valve and brain development, and most recently of dystroglycanopathy." (PMID 40879729, 2025).
Encephalopathy (1 paper, 2020). Encephalopathy is a term that means brain disease, damage, or malfunction. "As UDP-GlcA is the major product of the UGDH enzyme, it is possible that reduced levels of UDP-GlcA may trigger a cascade of secondary pathogenic events resulting in neurodevelopmental delay and encephalopathy." (PMID 32001716, 2020).
fibrosis (1 paper, 2023). the formation of excess fibrous connective tissue in an organ or tissue in a reparative or reactive process. "Decreases in the glucose and glucuronic acid content in the rat liver tissue in experimental fibrosis models were associated with activation of key enzymes of the glucuronic acid pathway UGDH and UGT." (PMID 37627599, 2023).
liver fibrosis (1 paper, 2023). "On the other hand, we found a significant increase in UGDH and UGT activity in all experimental groups except I/R, indicating the great importance of the glucuronate pathway in liver fibrosis in toxic and cholestatic damage." (PMID 37627599, 2023).
melanoma (1 paper, 2023). A malignant, usually aggressive tumor composed of atypical, neoplastic melanocytes. "Within tissue samples, the authors also correlated levels of hyaluronan and UGDH mRNA with different stages of melanoma development and thus suggested that UDP-sugar metabolism is critically linked with hyaluronan and may support progression of melanoma." (PMID 37769033, 2023). "Independent of UGDH, high HA levels are considered a marker of malignancy in several types of solid tumors including melanoma, bladder, lung, prostate, breast, and colon." (PMID 37769033, 2023).
nasopharyngeal carcinoma (1 paper, 2023). A carcinoma arising from the nasopharyngeal epithelium. "While they could not mechanistically explain this observation, it is nevertheless interesting as the AKT pathway has been shown to regulate UGDH expression in colorectal and nasopharyngeal cancer." (PMID 37769033, 2023). "Within nasopharyngeal carcinoma, (a tumor with high metastatic potential due, in part, to high expression levels of Epstein-Barr virus latent membrane protein 2A (LMP2A)), LMP2A-induced higher expression of UGDH, subsequently increased GAG synthesis." (PMID 37769033, 2023).
ovarian tumour (1 paper, 2020). "To examine the effect of UGDH silencing on ovarian tumour growth in vivo, we employed TOV21GHI cells to perform xenograft transplantation of immunodeficient mice in vivo." (PMID 32893977, 2020).
prostate tumor (1 paper, 2021). "Collectively, our results support a model in which UGDH expression levels can selectively control the androgen elimination pathway in prostate tumor cells, where excess UGDH drives castration resistance while reduction of UGDH may permit retention or re-establishment of androgen sensitivity." (PMID 34548906, 2021). "The impact of genetically manipulating UGDH expression in prostate tumor lines has not been previously examined in detail." (PMID 34548906, 2021).
psoriasis (1 paper, 2019). An autoimmune condition characterized by red, well-delineated plaques with silvery scales that are usually on the extensor surfaces and scalp. "As UGDH has not been linked to psoriasis previously, this protein was chosen for further analysis." (PMID 31388062, 2019). "UGDH has not been highlighted previously in association with psoriasis." (PMID 31388062, 2019).
renal carcinoma (1 paper, 2020). A carcinoma arising from the epithelium of the renal parenchyma or the renal pelvis. "In a report from The Human Protein Atlas, overexpressed UGDH is associated with poor survival rates in renal cancer." (PMID 32893977, 2020).
serous ovarian cancers (1 paper, 2023). "High UGDH expression was observed in high-grade serous ovarian cancers and a distinctive survival prognostic for UGDH expression was revealed when serous cancers were stratified by molecular subtype." (PMID 37858159, 2023).
steatosis (1 paper, 2023). Increased lipid within the cytoplasm of cells. "In addition to a propensity for liver damage, HFD-fed UGDH-deficient mice, in comparison to Ugdhf/f mice on the same diet, also exhibited greater levels of lipid accumulation and steatosis in the liver, as indicated by H&E and Oil red O staining, as well as by levels of hepatic TG and TC." (PMID 37169760, 2023). "However, in CD-HFD-fed UGDH-deficient mice, suppression of RIPK1 kinase was unable to reduce hepatic steatosis and inflammation." (PMID 37169760, 2023). "We first examined UGDH expression in the livers of human subjects without steatosis, with simple steatosis and with NASH." (PMID 37169760, 2023). "We found that steady-state UGDH protein levels were considerably lower in the livers of individuals with simple steatosis or NASH than in the nonsteatotic controls, and the NASH group had markedly lower UGDH expression than the simple steatosis group." (PMID 37169760, 2023).
triple-negative breast carcinoma (1 paper, 2021). An invasive breast carcinoma which is negative for expression of estrogen receptor (ER), progesterone receptor (PR), and human epidermal growth factor receptor 2 (HER2). "Higher levels of UGDH were correlated with worse prognosis in triple-negative breast cancer patients that received chemotherapy." (PMID 33572239, 2021). "We have observed that higher levels of UGDH expression were correlated with a worse prognosis (less survival) in patients with triple-negative breast cancer who have received chemotherapy." (PMID 33572239, 2021).